MIF (macrophage migration inhibitory factor)
Diseases named in the same sentence as MIF in open-access papers (continued):
Sharing a sentence is not in itself a finding about the gene and the disease.
glioblastoma (53 papers, 2007 to 2025). The most malignant astrocytic tumor (WHO grade IV). "Here, we find that the single-nucleotide polymorphism (SNP) rs755622 in the promoter of the cytokine macrophage migration inhibitory factor (MIF) is associated with increased leukocyte infiltration in glioblastoma." (PMID 37252795, 2023). "In vitro, exposure of the glioblastoma cells lines, U87 and U251, to hypoxia was associated to an increase in MIF and CXCR4 levels and to the induction of vasculogenic mimicry." (PMID 29707160, 2018). "Our bioinformatics analyses showed that loss of COX-2 activity and amplification of MIF is associated with transformed cells and brain tumors such as glioblastomas." (PMID 29247872, 2017). "Genetic deletion of MIF or inhibition of its nuclease activity in cancer cells significantly increases mutation frequency, reduces DNA synthesis, causes cell cycle delay, inhibits colony survival, and attenuates the growth of breast tumors, glioblastoma, and colon tumors in mice." (PMID 34012010, 2021). "High levels of MIF expression are observed in WHO grade IV glioblastomas and high-grade WHO grade III tumors, with the highest levels in the most malignant variants of GBM." (PMID 41159021, 2025). "MIF-directed treatments have the potential to complement existing therapies for primary CNS tumors, especially for malignant tumors such as glioblastoma and medulloblastoma." (PMID 39233830, 2024). "MIF knockdown by antisense transfection allowed for restoration of contact inhibition in human glioblastoma cell lines." (PMID 38178143, 2024). "Ibudilast is both an inhibitor of PDE2 and allosteric MIF antagonist that has shown efficacy in inducing cell cycle arrest and apoptosis in patient-derived glioblastoma cell lines, with clinical evidence for good CNS penetration." (PMID 38732068, 2024). "Differential expression patterns of CD74 and CXCR2 by MDSCs within and outside the glioblastoma TME further emphasize that MIF signaling is location-specific." (PMID 39233830, 2024). "Macrophage MIF expression is increased in glioblastoma and promotes malignant progression of the tumor as well as evasion of immune surveillance." (PMID 37088950, 2023). "A number of researchers suggest that MIF secreted by glioblastoma inhibits migration and maturation of DCs, suppressing the anti-tumor immune response." (PMID 35842634, 2022). "Further, glioblastoma stem cells produced high macrophage migration inhibitory factor (MIF), which increases the immuno‐suppressive enzyme Arg1 in MDSCs dependent on the CXCR2 axis." (PMID 36550571, 2022). "In a xenograft model of glioblastoma, the downregulation of MIF led to the increased density of macrophages at the edge of the tumor." (PMID 36552878, 2022). "MIF also promotes vasculogenic mimicry (VM) formation through the CXCR4-Akt-EMT pathway in glioblastoma to support malignant tumor progression." (PMID 35842634, 2022). "Hypoxia-induced MIF has been shown to be released in the glioblastoma TME promoting vasculogenic structure, and its expression correlates with the expression of VEGF." (PMID 34503065, 2021). "Recently, high levels of macrophage migration inhibitory factor (MIF) have been associated with tumor recurrence and poor survival, and MIF is now emerging as a promising anti-angiogenic target in glioblastoma." (PMID 34503065, 2021). "An additional example of paracrine-acting MIF driving MDSC phenotypes came from the Lathia group which identified that glioblastoma (GBM) cancer stem cell (CSC)-secreted MIF increases MDSC immune suppressive activity in an arginase 1-dependent manner." (PMID 33324425, 2020).
glioblastoma (continued). "It has also been found that anti-angiogenic therapy with bevacizumab is able to induce the depletion of MIF in glioblastoma cells." (PMID 29707160, 2018). "Glioblastoma xenograft tumors transduced with MIF expression grew slowly and exhibited low TAM infiltration in vivo." (PMID 29670046, 2018). "The increasing evidence supporting a role for MIF in cancer has also attracted attention on the contribution of this cytokine to the pathogenesis of glioblastoma and the possible development of anti-MIF tailored treatment for this disease." (PMID 29707160, 2018). "In the tissue specimens of bevacizumab-resistant glioblastoma patients, MIF expression was decreased and TAM infiltration was increased compared to those in bevacizumab-sensitive ones." (PMID 29670046, 2018). "Specifically, MIF is highly expressed in various types of tumors, including prostate, colon, melanoma and glioblastoma." (PMID 29113309, 2017). "Increased expression of MIF in glioblastomas and esophageal squamous-cell carcinoma showed adverse prognostic outcomes during chemotherapy." (PMID 29247872, 2017). "We wished to determine if concentrations of sulforaphane that inhibit MIF enzymatic function in vitro (5–10 μM) had obvious toxicity to normal leukocytes or glioblastoma cells." (PMID 28666020, 2017). "We showed that in vitro targeting MIF in cultures of human malignant glioblastoma cells by either antisense plasmid introduction or anti-MIF antibody treatment reduced the growth rates of tumor cells." (PMID 20038293, 2009). "In particular a strong increase of MIF expression in human glioblastoma multiforme has been reported by several investigators." (PMID 20038293, 2009). "Here we show that in vitro targeting MIF in cultures of human malignant glioblastoma cells by either antisense plasmid introduction or anti-MIF antibody treatment reduced the growth rates of tumor cells." (PMID 20038293, 2009). "Nuclear redistribution of MIF has been seen in tumor tissues from lung adenocarcinoma patients and glioblastoma multiforme tissue." (PMID 17650334, 2007). "MIF overexpression has been documented in glioblastoma (GBM)." (PMID 41472252, 2025). "The effects of MIF on glioblastoma development and progression extend to its prognostic utility." (PMID 39233830, 2024). "Lathia’s group showed an immunosuppressive role of MIF via influencing MDSCs in glioblastoma." (PMID 36672343, 2023). "However, recombinant human MIF increased autophagy in glioblastoma cells, and the knockout of endogenous MIF inhibited autophagy." (PMID 35280512, 2022). "In studies with glioblastoma xenograft tumors and co-culture strategies, it was demonstrated that macrophage migration inhibitory factor (MIF), which is secreted at high levels by CSCs, activated the immunosuppressive phenotype of MDSCs in a CXCR2-dependent manner." (PMID 34771577, 2021). "Furthermore, in glioblastoma CSCs, the secretion of the macrophage migration inhibitory factor (MIF) activates MDSCs and induces immunosuppression." (PMID 34062950, 2021). "In addition, add on treatment to temozolomide with the MIF inhibitor ibudilast significantly increased the survival in vivo, in a patient-derived xenograft model of glioblastoma." (PMID 32155795, 2020). "Furthermore, a strong positive correlation was demonstrated in glioblastoma cells between hypoxia-induced VM, macrophage migration inhibitory factor (MIF) and C-X-C motif chemokine receptor 4 (CXCR4) co-localization, and HIF-1α levels." (PMID 31772665, 2019).
glioblastoma (continued). "Bevacizumab, a monoclonal antibody that targets VEGF may also interact and neutralize MIF in glioblastomas, inducing the polarization of MOs into the M2-like phenotype that contributes to therapy resistance." (PMID 29875777, 2018). "Along with this line, in this paper, we have reviewed the evidence of the involvement of MIF in the etiopathogenesis and progression of glioblastoma and the preclinical data suggesting the possible use of specific MIF inhibition as a potential novel therapeutic strategy for brain tumors." (PMID 29707160, 2018). "In glioblastoma, MIF can also induce pro-inflammatory functions, including M1-like MO polarization." (PMID 29875777, 2018). "Furthermore, we showed the relevance of the enzymatic active site of MIF for the proliferation of glioblastoma cells by using the MIF-tautomerase inhibitor ISO-1." (PMID 20038293, 2009). "In this review, we will focus on MIF’s crucial role in neurological diseases such as multiple sclerosis (MS), Alzheimer’s disease (AD) and glioblastoma (GBM)." (PMID 38178143, 2024). "Negative regulators of MIF and downregulated miRNAs include miRNA-451 (prostate cancer, neuroblastoma, gastric carcinoma, and hepatocellular carcinoma), miRNA-144 and miRNA-1228 (hepatocellular carcinoma and gastric carcinoma), and miRNA-608 (lung adenocarcinoma and glioblastoma)." (PMID 38732068, 2024). "In conclusion, MIF can lead to malignant progression of GBM by inducing autophagy and evasion of DC monitoring in glioblastoma." (PMID 37088950, 2023). "Cultured human glioblastoma U87 cells, which normally do not express L1, were transduced with lentivirus, encoding the recombinant MIF-EGFP gene, for 48 h, then the cells were further transduced with adeno-associated virus mediating the expression of L1-70-Myc and Top1-HA for an additional 24 h." (PMID 35013124, 2022). "In glioblastoma, bevacizumab-induced VEGF depletion unexpectedly elevates macrophage migration inhibitory factor (MIF) at the tumor periphery, expanding TAM infiltration." (PMID 40693266, 2025). "As previously stated, there is a direct correlation between MIF/DDT and HIF-1α (Section 4.4 and Section 4.6), with MIF secretion during hypoxic conditions also being reported in glioblastoma." (PMID 36672343, 2023). "Recombinant human MIF (rhMIF) activates the RhoA‐ROCK1 pathway and promotes the formation of F‐actin fibers, thereby increasing autophagy in glioblastoma cells." (PMID 37088950, 2023). "High expression of MIF and CXCR4 in glioblastoma cells under hypoxia conditions is reported to promote EMT of glioblastoma cells via a MIF-CXCR4-AKT pathway." (PMID 35842634, 2022). "CSCs-derived MIF enhances the immunosuppressive function of MDSCs in a CXCR2-dependent manner, thereby promoting the proliferation, survival and immune evasion of glioblastoma cells." (PMID 35842634, 2022). "The chemokine genes MIF, CCL2, CXCL8, CX3CL1 and CXCL2 were all highly expressed by the six glioblastoma primary lines." (PMID 36430641, 2022). "As VEGF increases MIF production in a VEGFR-dependent manner, inhibition of the VEGF pathway directly depletes MIF expression, resulting in TAM recruitment and M2 polarization in bevacizumab-resistant glioblastoma patients." (PMID 29670046, 2018). "The MIF inhibitor ISO-1 inhibited G8 and G9 glioblastoma cells proliferation at 25-50 μM and also led to an up-regulation of MIF protein and its receptors expression, probably as a compensatory feedback of MIF function inhibition." (PMID 29707160, 2018). "The authors have also shown that inhibiting MIF intrinsic tautomerase activity by the small compound inhibitor ISO-1, reduced proliferation and mitogenic signaling in glioblastoma cells." (PMID 29707160, 2018). "In the glioblastoma TME, MIF impairs leukocyte activity against tumor cells." (PMID 39233830, 2024).
glioblastoma (continued). "Interestingly, MIF secreted by CSCs is reported to enhance immunosuppression mediated by MDSCs through binding the CXCR2 receptor, which facilitates glioblastoma immune evasion." (PMID 35842634, 2022). "Macrophage migration inhibitory factor (MIF) also triggers via CXCR4 and AKT EMT in glioblastoma." (PMID 29112161, 2017). "This is important evidence that ZIKVBR can block tumor immune evasion by targeting MIF, a factor that inhibits the increase in CD8 T cells number in the tumor microenvironment and reduces immune suppression in glioblastoma (GBM)." (PMID 34696533, 2021). "MIF and DDT play a pivotal role in aggressive glioblastoma multiforme (GBM)." (PMID 38732068, 2024).
Insulin resistance (47 papers, 2009 to 2026). Increased resistance towards insulin, that is, diminished effectiveness of insulin in reducing blood glucose levels. "MIF rs1007888 has been associated with insulin resistance and β-cell dysfunction, while ARAP1 rs1552224 has been linked to reduced insulin secretion." (PMID 41036138, 2025). "Normal MIF expression was found to be linked to metabolic dysfunction and insulin resistance induced by olanzapine, when compared to low MIF expression." (PMID 38531873, 2024). "This indirectly prevents adipocyte hypertrophy and tissue inflammation and attenuates the effect of cytokines implicated in insulin resistance (e.g., TNFα and MIF signaling), as observed herein." (PMID 34444996, 2021). "Researches showed that MIF-deficiency reduced chronic inflammation in white adipose tissue and impaired the development of insulin resistance." (PMID 32265835, 2020). "A positive association has been reported between MIF plasma levels, FFAs concentration, and insulin resistance." (PMID 32831068, 2020). "These associations with MIF have also been reported in earlier stages of T2D development (impaired glucose tolerance, insulin resistance), before overt T2D is present." (PMID 26124760, 2015). "Overall, circulating MIF seems to be associated with insulin resistance and overt T2D, and MIF levels rise with the severity of disease." (PMID 26124760, 2015). "MIF deficiency partially protects from high-fat diet induced insulin resistance by attenuating macrophage infiltration, ameliorating adipose inflammation, which improved adipocyte insulin resistance ex vivo." (PMID 25412423, 2014). "Plasma MIF levels are frequently associated with insulin resistance." (PMID 38802393, 2024). "We previously found that administering olanzapine (OLZ), a common AAP, as monotherapy over two months led to increased circulating MIF levels in first-episode SZ patients, and this rise was positively associated with elevated body weight gain, insulin resistance, and hyperlipidemia." (PMID 38802393, 2024). "Notably, the heightened MIF levels are closely linked to insulin resistance, with a primary reliance on increased blood insulin levels rather than glucose." (PMID 38802393, 2024). "Indeed, the polymorphisms FTO rs9939609, ADIPOQ rs2241766, and MIF rs755622 are strongly linked to the presence of insulin resistance." (PMID 35450164, 2022). "Both MCP-1 and MIF have also been implicated in the pathogenesis of insulin resistance." (PMID 30302090, 2018). "Plasma MIF higher in Pima Indians and associated with insulin resistance." (PMID 26124760, 2015). "In adipocytes, MIF-driven TNF-α secretion contributes to insulin resistance, while in endothelial cells, MIF disrupts insulin-mediated nitric oxide release, fostering endothelial insulin resistance." (PMID 41036138, 2025). "Macrophage migration inhibitory factor (MIF) rs1007888 is significantly associated with pancreatic β-cell function and insulin resistance in patients with gestational diabetes mellitus (GDM)." (PMID 41036138, 2025). "Plasma MIF levels demonstrate a positive correlation with insulin resistance in patients with type 2 diabetes (T2D)." (PMID 38802393, 2024). "Elevated plasma MIF levels displayed a notable correlation with insulin resistance (β = 0.024, p = 0.020), as well as with the levels of triglycerides (β = 0.019, p = 0.001) and total cholesterol (β = 0.012, p = 0.038) in the groups receiving AAPs." (PMID 38802393, 2024). "This shows that the higher BMI, the more serious the accumulation of adipocytes, the more MIF and insulin secretion, the more serious the impact on occurrence of insulin resistance and tumor progression." (PMID 34485124, 2021). "A variety of adipokines, such as leptin and MIF, are related to the occurrence of insulin resistance." (PMID 34485124, 2021). "In the same context, MIF stimulates the inflammatory adipocytokines; resistin and IL-6 both are key molecules in the development of insulin resistance." (PMID 27298517, 2016).